TNF (tumor necrosis factor)
Diseases named in the same sentence as TNF in open-access papers (continued):
Sharing a sentence is not in itself a finding about the gene and the disease.
gastritis (continued). "The results of the in vivo mouse acute gastritis model showed that ICE significantly reduced inflammatory lesions in the gastric mucosa and remarkably downregulated the expression of iNOS, TNF-α, IL-1β, and IL-6 mRNA in gastric tissue." (PMID 36386225, 2022). "Since we previously demonstrated Sumac biological activity in a model of tumor necrosis factor alpha (TNF-α)-induced skin inflammation, the present work is aimed at further demonstrating a potential role in inflammatory disorders, focusing on gastritis." (PMID 35565724, 2022). "The study results showed that TNF-α, IL-1β, IL-6, TLR4, and MBL2 are common among Covid-19, IBD, gastritis, and diarrhea." (PMID 35845309, 2022). "T helper-1 (Th1) cells and their signature cytokines, IL-1β, tumor necrosis factor (TNF)-α and particularly interferon (IFN)-γ, are essential for the development of gastritis." (PMID 34062919, 2021). "Focusing on Il-1β, IL-6, IL-8, IL-12, IL-18, and TNF-α, we analysed gene and protein levels to differentiate between H. pylori-infected and non-infected gastritis." (PMID 38561502, 2024). "In contrast, the IL-12, IL-18, and TNF-α levels were higher in H. pylori-infected gastritis compared to non-infected gastritis." (PMID 38561502, 2024). "In H. pylori infection-associated gastritis, the IL-1β, IL-6, and IL-8 were lower, whereas IL-12, IL-18, and TNF-α were higher than those in gastritis without H. pylori infection." (PMID 38561502, 2024). "In vitro results showed that Mb-ME could alleviate gastritis and relieve the protein expression of p-Src, p-Syk, and COX-2, as well as the gene expression of COX-2 and TNF-α." (PMID 35270116, 2022). "FRVE significantly reduced H. pylori‐induced gastritis, although such effect was not due to altered IL‐1β or TNF‐α expression in mice." (PMID 33598173, 2021). "In addition, similar to phenotype of Cc-ME in gastritis model, increased mRNA levels of inflammatory genes (COX-2, IFN-β, IFN-γ, IL-1β, IL-6, iNOS, and TNF-α) were also significantly suppressed in both Cc-ME- and ranitidine-treated groups." (PMID 29725354, 2018). "Helicobacter pylori induces a large increase in TNF-α expression in patients with gastritis, regardless of tissue inflammation, but after the tissue becomes neoplastic, the presence of bacteria did not influence expression." (PMID 26719751, 2015). "Immunosuppressive agents, such as TNF-α inhibitors (e.g., infliximab) or integrin blockers (e.g., vedolizumab), may be used steroid-resistant gastritis if there is no improvement within 2 to 3 days after intravenous steroid administration." (PMID 41142620, 2025). "In addition, FRVE significantly reduced H. pylori‐induced gastritis, although such effect was not due to altered IL‐1β or TNF‐α expression in mice." (PMID 33598173, 2021). "Ours results show that the presence of Helicobacter pylori induces a large increase in TNF-α expression in patients with gastritis, regardless of tissue inflammation, but after the tissue becomes neoplastic, the presence of bacteria did not influence expression." (PMID 26719751, 2015). "In parallel, H. pylori-administered mice demonstrated gastritis with inflammatory responses, as indicated by the prominent histological scores based on inflammatory cell infiltration and epithelial damage and increased inflammatory cytokines (IL-6 and TNF-α, but not IL-10) in the stomach." (PMID 35955701, 2022). "In patients with non-ulcer dyspepsia, gastritis or peptic ulcers that were infected by H. pylori, a high secretion of IL-17, IFN-γ, IL-23, IL-6, IL-10, TNF-α, IL-21, IL-8, and IL-37 was reported." (PMID 35955936, 2022). "Quantitative real-time PCR (Q-PCR) analysis demonstrated that proinflammatory cytokines TNF-α and IL-12/23p40 were highly upregulated in gastritis-positive AID−/− mice, but not in AID+/+ or gastritis-negative AID−/− mice." (PMID 18716662, 2008).
gastritis (continued). "Moreover, other inflammatory cytokines and chemokines (IL-27, IFN-β, IL-1α, IL-23, IL-22P70, TNF-α, IL-17A, IL-10, IL-1β, and MCP-1) were not showed dose-dependent changed in DFMO-treated mice compared to gastritis mice group." (PMID 32231118, 2020).
cardiomyopathy (106 papers, 2007 to 2025). A disease of the heart muscle or myocardium proper. "The Wnt/β-catenin/RAS axis is also implicated in DOXO-induced cardiomyopathy, with TNF-α acting as an upstream stimulator.Inhibition of TNF-α using infliximab or rolipram has shown protective effects against DOXO-induced cardiomyopathy in animal models." (PMID 40064787, 2025). "Cats with CHF caused by cardiomyopathies (i.e., hypertrophic cardiomyopathy) have increased plasma concentrations of tumor necrosis factor alpha (TNF-α)." (PMID 33802401, 2021). "In the B cell-deficient mouse cardiomyopathy model, it was found that with the decrease in TNF-α, serum collagen I and III levels decreased, and the amount of collagen fibres deposited in the extracellular matrix decreased." (PMID 33407160, 2021). "In summary, our results show that CD4+CD25+ Treg from patients with severe cardiomyopathy display a deficient suppressive activity, leading to uncontrolled production of pro-inflammatory cytokines (TNF-α and IFN-γ) from leukocytes." (PMID 22545173, 2012). "Elevated local cardiac production and increased circulating levels of TNF-α have been implicated in cardiomyopathies of various etiologies." (PMID 21203448, 2010). "Short-term TNFα expression is thought to be an adaptive mechanism; whereas prolonged expression causes left ventricular dysfunction and cardiomyopathy leading to CHF propagation." (PMID 20224758, 2009). "It is already known that patients with sepsis-associated cardiomyopathy have an exacerbated inflammatory status that is characterized by elevated circulating levels of several cytokines, including the previously-mentioned IL-6 and TNF-α." (PMID 35888173, 2022). "Hyperglycemic rats had increased serum levels of adipokines (omentin, resistin, and TNF-α) and cardiomyopathy markers (cardiac troponin I and Creatine kinase-MB)." (PMID 38227584, 2024). "TNF-α and complement activation have been suggested as contributing factors to myocardial reperfusion injury and cardiomyopathy." (PMID 39457090, 2024). "Our data support the results obtained in a cohort of patients from Taiwan (patients with IVS4 + 919G > A in GLA), in which a significant increase in plasma concentration of TNF-α was shown in FD patients who presented with cardiomyopathy." (PMID 38892211, 2024). "In hyperglycemic rats, the level of fasting blood glucose, and serum level of resistin, omentin, TNF-α, and cardiomyopathy biomarkers significantly increased (P < 0.05)." (PMID 38227584, 2024). "Infections such as spontaneous bacterial peritonitis (SBP) release tumor necrosis factor alpha (TNF) that can exacerbate cardiomyopathy." (PMID 38202206, 2023). "LLLT can suppress circulating cytokines levels, in particular, tumor necrosis factor-α (TNF-α) and interleukin (IL)-6, these cytokines can promote progressive left ventricular (LV) dysfunction, LV remodeling, and cardiomyopathy." (PMID 36780088, 2023). "TNF-α is also involved in the activation of the RAAS system which has been implicated in worsening cardiac function and the development of cardiomyopathies." (PMID 36851240, 2023). "In LPS-treated mice, systemic inflammation and the consequent cardiomyopathy were verified by elevated plasma levels of TNFα, GDF-15, and cardiac troponin I, and by a decrease in the ejection fraction." (PMID 35059851, 2022). "NF-κB and TNFα were consistently upregulated in all studies included in our systematic review, which suggests (chronic) inflammation in anthracycline-induced cardiomyopathy." (PMID 34052857, 2021). "It has been reported that proinflammatory cytokines such as TNFα and IL-1 are elevated in SGs from patients with a variety of cardiomyopathies and correlated with prognosis and severity of CHF." (PMID 33884509, 2021). "Exercise training has been shown to elevate AKT phosphorylation in the dilated heart with cardiomyopathy and to attenuate the isoprenaline-stimulated NF-κB, TNF-α, IL-6, and TGF-β1 in the myocardium." (PMID 32354131, 2020).
cardiomyopathy (continued). "Higher frequencies of CD4+ IL-17A+ T-cells, lower levels of IL10 and IL10, and higher levels of IFNγ and TNFα are observed in individuals with more severe cardiomyopathy." (PMID 33193300, 2020). "TNF-α is particularly increased in chronic patients and is considered an important indicator of cardiomyopathy." (PMID 29662478, 2018). "TNF can also induce TNT formation between iPSC-derived MSC and cardiomyocytes for mitochondria transfer to attenuate the damage in mouse anthracycline-induced cardiomyopathy, which is regulated by TNF/NFκB/TNF-IP2 signaling pathway." (PMID 30079066, 2018). "Among studied cytokines, some were associated with general susceptibility to T. cruzi infection (IFN-γ, MIF, IL-4, TNF, TGF-β, and IL-18) and others with cardiomyopathy development (TNF, IL-1, BAT1, MCP-1, LT-α, IL-12, and IL-10)." (PMID 29670670, 2018). "In chronic T. cruzi infection, systemic TNF has emerged as a key cytokine in the pathogenesis of cardiomyopathy and the dysregulation of the immune response in the spleen and bone marrow." (PMID 28877735, 2017). "Bones, tumors, and cardiomyopathy are examples of niches and conditions that contain MSCs and are enriched with tumor necrosis factor α (TNFα) and transforming growth factor β1 (TGFβ1)." (PMID 28553282, 2017). "IFN-γ, TNF-α and IL6 cytokines secretion levels were higher in patients at the asymptomatic phase of the disease than in Chagas patients with associated cardiomyopathy." (PMID 25816096, 2015). "Dox-induced cardiomyopathy is also associated with increased levels of the MMP2- and 9, and pro-inflmammatory cytokines TNF-α, IL-1β, and IL-6 as similar to the results observed in kidney." (PMID 25742619, 2015). "In the context of a mouse model for tumor necrosis factor alpha-induced cardiomyopathy, it was found that increased expression of TNF-alpha leads to degradation and changes in the subcellular distribution of desmin and to pathological aggregate formation." (PMID 23143191, 2013). "Cultures of PBMC from patients with moderate and severe cardiomyopathy produced high levels of TNF-α, IFN-γ and low levels of IL-10, when compared to mild cardiomyopathy or cardiomyopathy-free patients." (PMID 22545173, 2012). "It has been shown that tumor necrosis factor (TNF-α) is upregulated in a number of cardiomyopathies inducing adverse cardiac remodeling and dilation due to the degradation of the extracellular matrix by matrix metalloproteinases (MMPs)." (PMID 21912722, 2011). "Transgenic mice expressing a non-cleavable membrane bound TNFα have reduced adipose mass and cardiac-specific overexpression of TNFα in mice results in cardiomyopathy." (PMID 18070349, 2007). "The pro-inflammatory cytokine TNF-α plays a crucial role in lipid-overload-induced cardiomyopathy." (PMID 39125700, 2024). "Statins, polyunsaturated fatty acids, and adiponectin may be effective therapies for DMD cardiomyopathy due to their ability to modulate tumor necrosis factor-α and interleukin." (PMID 40729215, 2024). "Reduction of VCAM-1 and intercellular adhesion molecule 1 (ICAM-1) by CBD treatment has also been reported in an animal model of diabetes-induced cardiomyopathy, high glucose-induced endothelial cell barrier disruption, and in TNF-α exposed sinusoidal epithelial cell assays." (PMID 36109476, 2023). "In subjects with cardiomyopathy who were treated with ivabradine, inflammatory biomarkers, namely tumor necrosis factor α (TNFα), growth-differentiation factor 15 (GDF-15), heart-type fatty acid binding protein (H-FABP), and interleukin 6 (IL-6), were attenuated." (PMID 36769115, 2023). "Similarly, we observed persistent upregulation of the pro-inflammatory cytokine TNFα, which also implicates a chronic pro-inflammatory state in anthracycline-induced cardiomyopathy." (PMID 34052857, 2021). "For example, over-expression of TNF-α, IL-1 and IL-6 in the immune system could lead to vascular leakage, systemic fatigue, cardiomyopathy and acute-phase protein synthesis." (PMID 34457338, 2021).
cardiomyopathy (continued). "Additionally, MSE also downregulated the expression of inflammatory markers such as TNF-α and IL-6 which were known to be critical in cardiomyopathy." (PMID 33747350, 2021). "Although locally synthesized TNF-α in cardiomyopathy may be remarkable, the level of TNF-α correlates more with the functional class rather than the LVEF, indicating perhaps that the heart is not the only source of this cytokine." (PMID 31998452, 2019). "CLP-induced cardiomyopathy, indicated by reduced dP/dt and increased cardiac troponin I phosphorylation, was attenuated by BRL44408, this was associated with reduced cardiac TNF-α and endothelial VCAM-1 expression, cardiomyocyte apoptosis and related signal molecule phosphorylation." (PMID 29615637, 2018). "A balance between host and parasite in asymptomatic cases may be maintained by expression of the anti-inflammatory cytokine IL-10, while cardiomyopathy is associated with inflammation triggered by IFN-gamma and TNF-alpha." (PMID 29281643, 2017). "Surprisingly, in cardiomyopathy patients, TNF-α levels were inversely correlated with LVEF." (PMID 24603474, 2014). "In addition, TNF-α production levels were lower in free/mild cardiomyopathy patients than in patients with moderate/severe cardiomyopathy." (PMID 22545173, 2012). "TNFα may be involved in progression of CHF because high levels of TNFα can induce left ventricular dysfunction, ventricular remodelling, cardiomyopathy, and pulmonary edema." (PMID 20224758, 2009). "For instance, overexpressed TNF-α, IL-1, and IL-6 could induce fever, general malaise, fatigue, vascular leakage, diarrhea, cardiomyopathy, lung injury, vascular leakage, acute-phase protein synthesis, complement system activation, and diffuse intravascular coagulation." (PMID 33553280, 2020). "Altogether, these findings suggest that TNF may be merely a component of a complex inflammatory profile associated with cardiomyopathy in CD, rather than a single determinant factor." (PMID 29768622, 2018). "It is already established that elevation in inflammatory mediators in the heart is associated with cardiac dysfunction, but it has been contentious as to whether TNF-α mediates inflammation and fibrosis in doxorubicin-induced cardiomyopathy and the failing heart." (PMID 22348065, 2012). "This would confirm the role that certain inflammatory cytokines (IFNγ, TNFα, or CCL3) play in the induction of cardiac pathologies (cardiomyopathy and QTc prolongation) in the disease." (PMID 40623042, 2025). "Beta-blockers are shown to effectively suppress inflammatory molecules, such as TNFα and IL10 in cardiomyopathy patients." (PMID 38216681, 2024). "To demonstrate the anti-inflammatory effects of AKBA, we assessed the production levels of proinflammatory cytokines, including TNF-α, IL-6, IL-1β, and PGE2, which contributed to LPS-induced cardiomyopathy." (PMID 35399644, 2022). "In two studies performed on norepinephrine-induced cardiomyopathy and HF models in rats, it was found that RDN can inhibit transforming growth factor-β1, MMP2, collagen I, and inflammatory cytokines CRP and TNF-α." (PMID 36035484, 2022). "Elevated levels of TNF-α and IL-6 have indeed been reported in BTHS patients, further exacerbating their cardiomyopathy." (PMID 33001359, 2021). "Lnc‐MEG3 expression was positively correlated with cardiomyopathy, APACHE II score, SOFA score, Scr, TNF‐α, IL‐1β, IL‐6, and IL‐17, 28‐day deaths, while negatively correlated with albumin." (PMID 34956235, 2021). "Our data confirmed that PBMC from the group of moderate/severe cardiomyopathy patients produce more IFN-γ and TNF-α and less IL-10 than the cells obtained from the other groups." (PMID 22545173, 2012). "Levels of TNF-α and iNOS were significantly higher in HIV-positive individuals with cardiomyopathy on endomyocardial biopsy than in HIV-negative cardiomyopathy patients." (PMID 19936197, 2008).
cardiomyopathy (continued). "HIV-mediated cytokine dysregulation may lead to an increase in tumor necrosis factor-alpha (TNF-alpha), interleukin-1 (IL-1), and IL-6, and thus be an important contributor to the development of HIV cardiomyopathy." (PMID 36127962, 2022). "In response to pressure overload and in comparison to wild-type mice, TNF knockout mice exhibited reduced collagenase activity, lower superoxide levels and PI3K activity, attenuated cardiomyopathy, and reduced interstitial and perivascular fibrosis as well as cardiac remodeling." (PMID 35892569, 2022). "Despite a comprehensive understanding of the function of TNF-α, the role of TNF-α in calpain activation in stress cardiomyopathy has not been clarified." (PMID 35013173, 2022). "Given that BTHS is characterized by cardiomyopathies, it would not be surprising to expect increased levels of TNF-α and IL-6 in this disease state." (PMID 33001359, 2021). "Given that BTHS is characterized by cardiomyopathies, it would not be surprising to observe increased levels of TNF-α and IL-6 in this disease state." (PMID 33001359, 2021). "On the other hand, although circulating TNF-α and IL-6 levels are known to increase in human cardiomyopathy, this study did not detect an increase in SAA concentration in cardiomyopathy." (PMID 32326517, 2020). "Increased TNF-α levels reduce PGC-1α and pyruvate dehydrogenase kinase (PDK4) expression in human cardiac AC16 cells in vitro as well as in heart of TNF1.6 mice, a murine model of cardiac-specific TNF-α overexpression and cytokine-induced cardiomyopathy." (PMID 31440740, 2019). "Gene expression levels for TNFα were on the limit of detection by qPCR for both control and takotsubo-like cardiomyopathy animals (data not included)." (PMID 30623136, 2018). "Systemic cytokine levels were low (IL-6 and IL-10) or undetectable (TNF-α) with or without induction of takotsubo-like cardiomyopathy." (PMID 30623136, 2018). "In our study, however, no significant changes were found in either the serum or cardiac levels for IL-6 and cardiac TNF-α, suggesting that inflammation is not the key factor of the early changes related to cardiomyopathy." (PMID 23497124, 2013). "Moreover, studies in patients with dilated cardiomyopathy reported a significant increase of TNF-α among these individuals when compared with healthy controls, suggesting that the elevation of TNF-α could be an immune pathogenic mechanism in the progression to cardiomyopathy." (PMID 22545173, 2012). "The cultures of PBMC from patients with moderate/severe cardiomyopathy produced higher IFN-γ and TNF-α, and lower IL-10 levels than those observed in PBMC culture from free/mild cardiomyopathy patients, which is in accordance with previous reports by other researchers." (PMID 22545173, 2012). "In addition, the response to T. cruzi antigen regarding the production of TNF-α and IFN-γ was higher in patients with moderate/severe cardiomyopathy." (PMID 22545173, 2012). "Also, both CCC patients and long-term infected subjects without evidence of cardiomyopathy showed enhanced concentration of TNF-α in blood compared to healthy people (324.6±41.4 and 344.3±79.4 vs. 146.9±14.8 pg/ml, respectively)." (PMID 23451183, 2013). "Moreover, other SNP related to other cytokines that could be related to susceptibility to T. cruzi infection (IFN-γ, MIF, IL-4, TNF, TGF-β, and IL-18) or cardiomyopathy development (TNF, IL-1, BAT1, MCP-1, LT-α, IL-12, and IL-10) were not studied." (PMID 29670670, 2018). "Analysis of serum samples further showed elevated soluble MD2, inflammatory cytokines TNF-α and IL-6, and MD2-AGE complexes in diabetic subjects with DCM and without cardiomyopathy, compared with healthy samples." (PMID 32358497, 2020).